OTUD7B (OTU deubiquitinase 7B)
Description:
Negative regulator of the non-canonical NF-kappa-B pathway that acts by mediating deubiquitination of TRAF3, an inhibitor of the NF-kappa-B pathway, thereby acting as a negative regulator of B-cell responses. In response to non-canonical NF-kappa-B stimuli, deubiquitinates 'Lys-48'-linked polyubiquitin chains of TRAF3, preventing TRAF3 proteolysis and over-activation of non-canonical NF-kappa-B (By similarity). Negatively regulates mucosal immunity against infections (By similarity). Deubiquitinates ZAP70, and thereby regulates T cell receptor (TCR) signaling that leads to the activation of NF-kappa-B. Plays a role in T cell homeostasis and is required for normal T cell responses, including production of IFNG and IL2 (By similarity). Mediates deubiquitination of EGFR. Has deubiquitinating activity toward 'Lys-11', 'Lys-48' and 'Lys-63'-linked polyubiquitin chains. Has a much higher catalytic rate with 'Lys-11'-linked polyubiquitin chains (in vitro); however the physiological significance of these data are unsure. Hydrolyzes both linear and branched forms of polyubiquitin. Acts as a regulator of mTORC1 and mTORC2 assembly by mediating 'Lys-63'-linked deubiquitination of MLST8, thereby promoting assembly of the mTORC2 complex, while inhibiting formation of the mTORC1 complex.
Synonyms: Cezanne; ZA20D1
Tractability: PROTAC: ubiquitination databases record sites on it.
Target class: Enzyme; Hydrolase
Gene: Protein-coding gene on chromosome 1 (149,937,812 to 150,010,758, reverse strand). Ensembl gene ENSG00000264522.
Subcellular location: Cytoplasm; Nucleus
Subcellular location (Human Protein Atlas): Microtubules; Cytokinetic bridge; Mitotic spindle
Pathways (Reactome):
Signal Transduction: Regulation of TNFR1 signaling; TNFR1-induced NF-kappa-B signaling pathway; TNFR1-induced proapoptotic signaling
Metabolism of proteins: Ovarian tumor domain proteases
Gene Ontology:
Molecular function: cysteine-type deubiquitinase activity; K48-linked deubiquitinase activity; protein binding; cysteine-type peptidase activity; K63-linked polyubiquitin modification-dependent protein binding; DNA binding; zinc ion binding
Biological process: negative regulation of canonical NF-kappaB signal transduction; negative regulation of interleukin-8 production; negative regulation of protein localization to nucleus; negative regulation of TORC1 signaling; negative regulation of transcription by RNA polymerase II; positive regulation of TORC2 signaling; protein K11-linked deubiquitination; protein K48-linked deubiquitination; protein K63-linked deubiquitination; mucosal immune response; protein deubiquitination; protein deubiquitination involved in ubiquitin-dependent protein catabolic process
Cellular component: cytoplasm; nucleus; cytosol
Genetic constraint (gnomAD): Loss-of-function variants: 24 observed, 64.21 expected, observed/expected ratio (o/e) 0.37, 90% interval 0.27 to 0.53. The upper end of that interval is the gene's LOEUF score, 0.53, which puts it in group 2 of 6, group 1 being the genes least tolerant of losing a copy. Missense variants: 856 observed, 1,010.5 expected, observed/expected ratio (o/e) 0.85, 90% interval 0.8 to 0.9. Synonymous variants: 360 observed, 382.72 expected, observed/expected ratio (o/e) 0.94, 90% interval 0.86 to 1.03.
Homologues: Orthologues: chimpanzee OTUD7B (99% identical), macaque OTUD7B (98% identical), pig OTUD7B (94% identical), rabbit OTUD7B (94% identical), dog OTUD7B (93% identical), rat Otud7b (92% identical), mouse Otud7b (91% identical), guinea pig OTUD7B (88% identical), tropical clawed frog otud7b (66% identical), zebrafish otud7b (63% identical). Paralogues in human: OTUD7A (60% identical), TNFAIP3 (21% identical).
Diseases named in the same sentence as OTUD7B in open-access papers:
OTUD7B is named in the same sentence as 37 diseases in open-access papers, as found by Europe PMC text mining. Sharing a sentence is not in itself a finding about the gene and the disease. The quoted sentences say what the papers report.
breast carcinoma (17 papers, 2018 to 2025). "OTUD7B expression was found to be positively correlated with ERα in breast cancer and associated with poor prognosis." (PMID 34035221, 2021). "Based on the analysis of public data available in bc-GenExMiner, we found that OTUD7B was highly expressed in breast cancer tissue, especially in the ERα-positive subtype, and that high expression of OTUD7B was associated with poor prognosis." (PMID 34035221, 2021). "To examine the association of OTUD7B expression with breast cancer development, we next analyzed the transcriptional profile of OTUD7B, as well as other OTUD subtypes, in TCGA breast invasive carcinoma (BRCA)." (PMID 29416635, 2018). "OTUD7B mRNA levels in the high-risk cohort were significantly upregulated compared to the low-risk cohort among enrolled breast cancer patients." (PMID 29416635, 2018). "Moreover, OTUD7B upregulation significantly predicts an unfavorable risk for cancer recurrence/metastasis and is associated with a poor response to paclitaxel-based chemotherapy in breast cancer patients." (PMID 29416635, 2018). "Moreover, OTUD7B upregulation was appeared to predict an increased risk for cancer recurrence/metastasis in breast cancer patients who may exhibit a poor pathologic complete response to paclitaxel chemotherapy." (PMID 29416635, 2018). "Previous research has demonstrated that OTUD7B enhances the growth of breast cancer cells by stabilizing estrogen receptor α (ERα) and increasing its expression." (PMID 40746896, 2025). "For example, high OTUD7B expression in breast cancer acts to deubiquitinate LSD1, in turn activating histone deacetylase complexes to promote metastasis through epigenetic effects." (PMID 39990225, 2025). "The dual roles of OTU family members in specific cancers present intriguing mechanistic complexities, exemplified by OTUB1 in breast cancer, OTUD7B in lung cancer, and TNFAIP3 in CRC." (PMID 40469292, 2025). "Knockdown of either OTUD7B or LSD1 significantly reduced the expression of metastasis-associated genes and effectively suppressed the metastasis of breast cancer cells." (PMID 39394462, 2024). "For example, LSD1 is deubiquitinated and stabilized by USP28 and OTUD7B to support breast cancer stemness and metastasis." (PMID 39563370, 2024). "OTUD7B is overexpressed in human metastatic or high-grade breast cancer; the dysregulation of OTUD7B correlates with worse survival and cancer metastasis." (PMID 36351890, 2022). "In agreement with previous findings, where LSD1 has been found to facilitate metastasis across tumor types, OTUD7B depletion or LSD1 knockdown significantly suppresses the metastatic potential of breast cancer cells." (PMID 34050636, 2021). "Both proteins are overpresented in high‐grade or metastatic human breast cancer, highlighting a unique role of dysregulated OTUD7B signaling in driving breast cancer metastasis via LSD1." (PMID 34050636, 2021). "Stable knockdown of OTUD7B or USP7 markedly inhibited breast cancer cell proliferation and migration, reduced tumor growth and metastasis in vivo." (PMID 34035221, 2021). "Increased OTUD7B transcript levels have been found across human cancers, particularly in breast cancers based on TCGA database." (PMID 34050636, 2021). "Although previous evidence has shown that OTUD7B plays a crucial role in carcinogenesis, the molecular mechanisms of OTUD7B participation in the progression of breast cancer remain elusive." (PMID 34035221, 2021). "To determine the mechanism of OTUD7B in regulating breast cancer cell proliferation and migration by stabilizing ERα, we performed rescue experiments by ectopic-expressing ERα in OTUD7B- knockdown MCF-7 cells." (PMID 34035221, 2021). "The results of immunostaining demonstrated that ERα and OTUD7B colocalized both in the nucleus and cytosol of breast cancer cells." (PMID 34035221, 2021).
breast carcinoma (continued). "Both OTUD7B and LSD1 proteins are overpresented in high‐grade or metastatic human breast cancer, while dysregulation of either protein is associated with poor survival and metastasis." (PMID 34050636, 2021). "OTUD7B is overexpressed in the breast cancer tissue as compared with that in the paired adjacent normal tissue, and high expression of OTUD7B is associated with poor prognosis of breast cancer patients." (PMID 34035221, 2021). "To further confirm that ERα is required for OTUD7B to promote breast cancer cell proliferation and migration, we overexpressed OTUD7B in ERα-depleted cells." (PMID 34035221, 2021). "Our data further demonstrated that OTUD7B depletion dramatically decreased the proliferation and migration of ERα-positive breast cancer cells." (PMID 34035221, 2021). "In conclusion, our study revealed an interesting post-translational mechanism between ERα and OTUD7B in ERα-positive breast cancer." (PMID 34035221, 2021). "Depletion of OTUD7B decreased ERα protein level, the expression of ERα target genes, and the activity of estrogen response element in breast cancer cells." (PMID 34035221, 2021). "In the present study, we examined the role of OTUD7B in ERα-positive breast cancer cells and identified OTUD7B as the deubiquitinase to mediate ERα deubiquitination." (PMID 34035221, 2021). "In this study, we identified that OTUD7B, which was highly expressed in human breast cancer samples, was a novel ERα co-regulator through post-translational modification." (PMID 34035221, 2021). "As the previous reports, OTUD7B regulated deubiquitination and endocytosis of EGFR associated with breast cancer proliferation, migration and malignancy." (PMID 31747939, 2019). "Our data showed that OTUD7B upregulation was significantly associates with a poor RFS rate in patients with HER2-positive and basal-like breast cancers; the worst HR was observed in patients with basal-like breast cancer compared to other subtypes." (PMID 29416635, 2018). "In comparison, we analyzed the transcriptional profile of OTUD7B in breast tumors derived from breast cancer patients receiving pre-operative paclitaxel-based chemotherapy." (PMID 29416635, 2018). "We next evaluated the prognostic significance of OTUD7B in breast cancer patients who received paclitaxel-based chemotherapy." (PMID 29416635, 2018). "Intriguingly, compared to other OTUDs, OTUD7B transcript in tumors was significantly higher than that of normal tissues derived from patients with breast cancer." (PMID 29416635, 2018). "Moreover, studies have shown that depletion of OTUD7B markedly reduces the proliferation and migration capabilities of ERα-positive breast cancer cells, whereas overexpression of ERα can counteract the inhibitory effects induced by OTUD7B depletion." (PMID 40746896, 2025). "Previous studies indicate that OTUD7B is widely distributed among human cancers where it is often highly expressed in gastric cancers 17, pancreatic cancers 18, 19, breast cancers 13, 20, 21, and lung cancers 16, 22, 23, serving to exert cancer-promoting effects." (PMID 39990225, 2025). "OTUD6A, OTUD6B and OTUD7B play an essential role in breast cancer occurrence and metastasis." (PMID 37667382, 2023). "Increased OTUD7B expression is observed in breast cancer and lung cancer." (PMID 36672466, 2023). "We next examined the role of OTUD7B in regulating breast cancer progression." (PMID 34035221, 2021). "OTUD7B was highly expressed in breast cancer samples, especially in the luminal A subtype." (PMID 34035221, 2021). "In addition, OTUD7B depletion significantly decreased ERα-positive breast cancer cell proliferation and migration." (PMID 34035221, 2021). "Overall, our study has demonstrated that OTUD7B is a novel deubiquitinating enzyme of ERα and may prove to be a potential target for breast cancer intervention." (PMID 34035221, 2021).
breast carcinoma (continued). "Targeting the OTUD7B–ERα complex may prove to be a potential approach to treat patients with ERα-positive breast cancer." (PMID 34035221, 2021). "As ERα signaling plays a central role in ERα-positive breast cancer cell proliferation, OTUD7B may be a potential target for breast cancer intervention." (PMID 34035221, 2021). "Moreover, among OTUD subtypes, the level of OTUD7B mRNA was detected to be much abundant in primary tumors compared to normal tissues derived from patients with breast cancer." (PMID 29416635, 2018). "Moreover, we found that OTUD7B upregulation was significantly detected in primary breast cancer tissues compared to normal breast tissues but inversely correlated with tumor growth in TNBC cells." (PMID 29416635, 2018). "Since Let-7 microRNA has been shown to inhibit CASP3 expression, thereby promoting chemoresistance, and be negatively regulated by the NF-kB-Lin28 axis in breast cancer cells, we next analyzed the transcriptional profiles of OTUD7B, CASP3 and LIN28 in TNBC tissues." (PMID 29416635, 2018). "Interestingly, OTUD7B is also known to stabilize estrogen receptor α (ERα), and its depletion results in degradation of ERα and suppression of 17β-estradiol (E2) signaling in breast cancer cells." (PMID 40479062, 2025). "Consequently, OTUD7B deficiency impairs genome‐wide LSD1 occupancy and enhances the methylation of H3K4/H3K9, therefore profoundly impacting global gene expression and abrogating breast cancer metastasis." (PMID 34050636, 2021). "Furthermore, several lines of evidence, including aberrant expression of OTUD7B, and its tight correlation with high tumor grades and shorter metastasis free survival, indicate OTUD7B as a potential marker for predicting adverse prognosis in breast cancer patients." (PMID 34050636, 2021). "Our results demonstrated that depletion of OTUD7B significantly decreased cell proliferation and increased the population in G1 phases, indicating that OTUD7B may regulate G1-to-S transition in ERα-positive breast cancer cells." (PMID 34035221, 2021). "Other DUBs, including OTUD7B and MINDY1, are over-expressed in breast cancer and support ERα stability by removing and K11- and K48-linked ubiquitin chains, with OTUD7B expression being associated with poor prognosis." (PMID 40641933, 2025). "In breast cancer (BC), OTUD5, YOD1, OTUD6A, OTUD7B, ZRANB1, and TNFAIP3 were characterized as carcinogenic drivers." (PMID 40469292, 2025). "Degradation of LSD1, driven by OTUD7B depletion, impaired lung metastasis of LM2 breast cancer cells." (PMID 40479062, 2025). "This group revealed elevated levels of both the OTUD7B and LSD1 proteins in breast cancer patients and reported that these elevated levels were associated with advanced tumor stage, lymph node metastasis, and poor overall survival outcomes." (PMID 39394462, 2024). "Ovarian tumor domain-containing 7B (OTUD7B) is a DUB of the OTU protein superfamily and plays an important role in the development of lung cancer, breast cancer, and hepatocellular carcinoma." (PMID 36351890, 2022). "Immunohistochemical (IHC) staining detected profoundly elevated protein expression of both OTUD7B and LSD1 in 405 cases of primary breast cancer samples, strongly correlating with their histological grades." (PMID 34050636, 2021). "In the present study, we identified OTU domain-containing 7B (OTUD7B), a deubiquitylase belonging to A20 subgroup of ovarian tumor protein superfamily, as a bona fide deubiquitylase of ERα in breast cancer." (PMID 34035221, 2021). "Our findings not only suggest that OTUD7B could be a prognostic biomarker for paclitaxel efficacy but also imply that targeting OTUD7B may be a new strategy to enhance the anti-cancer effectiveness of paclitaxel-based chemotherapy against breast cancer, particularly TNBCs." (PMID 29416635, 2018).
breast carcinoma (continued). "Using the SurvExpress database, we found that high-levels of OTUD7B mRNA expression significantly correlated with poor RFS rates, with a hazard ratio (HR) of 1.4 in 1901 breast cancer patients." (PMID 29416635, 2018). "Thus, OTUD7B plays a unique partner‐switching role in maintaining the integrity of LSD1/CoREST corepressor complex, LSD1 turnover, and breast cancer metastasis." (PMID 34050636, 2021). "Conversely, OTUD7B depletion in several breast cancer cell lines profoundly decreased LSD1 protein level, without affecting LSD1 mRNA expression." (PMID 34050636, 2021). "Using the K-M Plotter database, we found that OTUD7B upregulation reflected an unfavorable prognosis in terms of RFS probability in patients receiving pre-operative paclitaxel chemotherapy with unclassified and basal-like breast cancer." (PMID 29416635, 2018). "On the other hand, OTUD7B upregulation more significantly (p < 0.05) predicted a poor RFS probability in patients receiving post-operative paclitaxel chemotherapy with unclassified and basal-like breast cancer." (PMID 29416635, 2018).